FAP (fibroblast activation protein alpha)
Diseases named in the same sentence as FAP in open-access papers (continued):
Sharing a sentence is not in itself a finding about the gene and the disease.
tumor (continued). "Our study has unveiled varying degrees of FAP expression across different tumor types and subtypes." (PMID 38558814, 2024). "FAP-targeted radioligand therapy represents a novel therapeutic approach to targeting the CCA tumor microenvironment in FAP expressing CCA and may be useful in combination with other CCA molecular-targeted or immunotherapies." (PMID 39664608, 2024). "In addition, the CCK8 and colony formation assays showed that FAP overexpression increased the proliferation ability of tumor cells, while the Transwell and wound healing assays suggested that FAP upregulation promoted the migration of tumor cells." (PMID 38740736, 2024). "Additionally, the fusion vaccine increased infiltration of the tumor by CTLs, while reducing the number of FAPα+ CAFS and MDSCs." (PMID 39081320, 2024). "Consequently, FAP serves as both a robust marker for CAFs identification and a promising therapeutic target to disrupt tumor-stroma interactions and counter tumor progression." (PMID 38826849, 2024). "Among the proteins successfully targeted by functionalized lanthanide nanoparticles are folic receptors, fibroblast activation protein (FAP), gastrin-releasing peptide receptor (GRP-R), prostate-specific membrane antigen (PSMA), and integrins associated with tumor neovasculature." (PMID 38334567, 2024). "One possible reason is the addition of the succinic acid linker, which might have interfered with the binding of our tracers to FAP, thus decreasing the tumor uptake." (PMID 38398552, 2024). "In addition, the on-chip expression profiling showed that the expression of the hepatic stellate cell-related genes FAP, SPARC, and TNC, especially FAP, was upregulated in tumor tissues compared to normal tissues." (PMID 38740736, 2024). "The novel SMDC was electively delivered more than 10% injected dose per gram of MMAE to FAP-positive tumors, with a tumor-to-kidney ratio of 16:1 at 24 h post-injection, which was identified as the best performing SMDC, which has now been prioritized for further clinical development." (PMID 38566971, 2024). "Likewise, and quite interestingly, for the BxPC-3 model, FAP was expressed in the tumor cells (yellow arrows) and the stromal cells in 4- and 8-week-old tumors (blue arrows)." (PMID 38891809, 2024). "FAP is upregulated in cancer-associated fibroblasts, which produce immunosuppressive factors such as transforming growth factor-β (TGF-β), creating an immunosuppressive tumor microenvironment that can confer resistance to immunotherapy." (PMID 39283414, 2024). "However, the novel cyclic peptide-based FAP analogue, FAP-2286, showed a significantly slower clearance from the stroma of the tumor tissue, as seen in xenografted SCID beige mice, when radiolabeled with lutetium-177 compared to [177Lu]Lu-FAPI-46." (PMID 39338305, 2024). "However, a difference in pharmacokinetics was observed; a more rapid uptake of [177Lu]Lu-eFAP-6 in the FAP-positive tumor compared to [177Lu]Lu-FAPI-46 was measured (6.4 ± 1.1% ID/g and 5.0 ± 1.7% ID/g 1 h post injection (p.i.), respectively)." (PMID 39073475, 2024). "Immunofluorescent histological analysis of the LL/2 tumors confirmed the presence of α-SMA+ and FAP+ cells, and a heat map analysis showed that FAP+ cells were concentrated predominantly at the stromal margin near the invasive front of the tumor." (PMID 38275890, 2024). "This might in part be due to higher tumor-to-background ratios and expression of FAP in different portions of the tumor compared to FDG as well as to summative effects of the two tracers." (PMID 37584717, 2024). "Similarly, anti-FAP VHHs that are conjugated to 131I or 225Ac were able to limit tumor growth and enhance the survival of mice bearing FAP-expressing tumors." (PMID 38254860, 2024). "Moreover, an orally administered DNA vaccine targeting FAP-depleted CAFs decreases type I collagen content, restricting the growth and metastasis of primary tumor cells promoting multidrug resistance in mice." (PMID 38693104, 2024).
tumor (continued). "Furthermore, FAP-targeted NIR-PIT treated mice showed significant tumor regression in the CAF-rich tumor model accompanied by an increase in CD8+ tumor infiltrating lymphocytes (TILs)." (PMID 38555315, 2024). "Consequently, FAP-specific inhibitors were initially developed as anticancer drugs and subsequently advanced into tumor-targeting therapies." (PMID 39201021, 2024). "Nevertheless, the association between the upregulation of cytokines TGF-β, IL-4/IL-13, IL-10, IL-6, and IL-2 and the overexpression of FAP across multiple tumor types highlights a crucial link between FAP+ CAFs, tumor progression, and evasion of immune surveillance." (PMID 39035007, 2024). "Most of the ligand and receptor genes are usually associated with worse patient survival, implying that the interaction between TAMs and FAP+ CAFs might be tumor-promoting." (PMID 39239526, 2024). "Thus, we analyzed the relationship between FAP expression and tumor staging, immune infiltration, and biological function of 33 tumors." (PMID 39055892, 2024). "Importantly, circNOX4 fuels tumor growth and metastasis by activating the fibroblast niche via the miR-329-5p/FAP/IL-6 axis." (PMID 38459511, 2024). "We now focus on the immune response after the localized killing of CAFs and hypothesize that FAP-targeted NIR-PIT reduces tumor immunosuppression as one mechanism of its anti-tumor activity." (PMID 38555315, 2024). "The potential impact of these CAF subpopulations on tumor growth and on FAP imaging is still unknown and needs further elucidation." (PMID 40604259, 2024). "For instance, CXCL12 secreted by FAP+ CAFs decreases tumor infiltration of CD8+ T cells." (PMID 38279300, 2024). "FAP+ CAFs are the main repository for CXCL12 in PDAC tumor microenvironment: CXCL12 promotes T cell spatial exclusion, and pharmacological inhibition of CXCL12-CXCR4 interaction results in T cell accumulation in tumor tissue and fostering of immune checkpoint blockade." (PMID 39575252, 2024). "Serving as the predominant CAF subclusters, FAP+ CAFs were found to be enriched at the tumor border in HCC but diffusely distributed in ICC, which may be related to the formation of a tumor capsule." (PMID 39239526, 2024). "Additionally, we showed that FAP+ CAFs secrete TGF-β and lead to increased expression of PD-L1 and CD73, all markers associated with tumor immunosuppression." (PMID 38555315, 2024). "Gallium-68-labeled FAP-2286 demonstrates remarkable efficacy in tumor imaging." (PMID 38543239, 2024). "Whether FAP could promote tumor progression through some specific molecular mechanisms remains to be further explored." (PMID 39055892, 2024). "Similarly, MMTV-PyVT tumor growth was significantly suppressed in the anti-FAP NIR-PIT group compared with anti-FAP Ab alone or an untreated control group." (PMID 38275890, 2024). "Moreover, co‐culture experiments demonstrated that FAP‐CAR‐T cells can induce specific targeting of FAP+ tumor cells and bystander killing of FAP− tumor cells while sparing non‐malignant ECFCs within the same culture well." (PMID 38975278, 2024). "Immunohistochemical (IHC) staining analysis of SSTR2 and FAP expression in tumor tissues." (PMID 39770488, 2024). "Moreover, the combination of eNVs-FAP with the ferroptosis agonist RSL3 enhanced the ferroptosis response by increasing LPO levels in tumor tissues, resulting in a synergistic anti-tumor effect." (PMID 39174509, 2024). "This phenomenon could arise from non-specific binding of blood components, such as lipoproteins, which may overshadow the binding to FAP, hindering its conversion into the tumor tissue." (PMID 38695960, 2024). "Likewise, clinical research on a FAP-targeted cancer vaccine has shown promising safety profiles and tumor engagement, enhancing CD8+ T cell-mediated antitumor immunity." (PMID 38693104, 2024).
tumor (continued). "Notably, compared with tumors with high SUVmax by 68Ga-FAPI PET imaging, 68Ga-FAPI PET/CT–negative tumors showed low FAP-α protein expression and contained a significantly higher number of tumor-infiltrating CD8+ T cells and CD4+ T cells." (PMID 38175716, 2024). "We analyzed FAP across 1216 tissue samples covering 23 tumor types and 70 subtypes." (PMID 38558814, 2024). "Additionally, they were found to enhance the infiltration of effector T cells into target tumour cells and FAP‐positive CAFs (FAP+CAFs)." (PMID 38572668, 2024). "In addition, patients in the C4 group intended to have immune cell exclusion and increase of FAP (a signal of thick matrix around tumor and hindering CD8+ T lymphocyte infiltrates) 15,16." (PMID 38977778, 2024). "FAP overexpression has been observed in at least 28 different tumor types, however tracer uptake in normal tissues including the salivary glands, thyroid, and oral mucosa could complicate therapeutic applications 9,38." (PMID 39479448, 2024). "However, efforts have been made to increase CAR-T efficacy and safety by directing delivery locally to the surgical site and by targeting proteins overexpressed in HNSCC tumor tissue compared to local adjacent tissue, namely FAP, HER3, and NKGD2." (PMID 38398094, 2024). "Therefore, the longer half-life, better tissue permeability, and lower toxicity of FAP-targeted peptides and antibodies relative to small molecule tracers make them a more effective choice for tumor imaging and treatment." (PMID 38543239, 2024). "Therefore, the intensity of the FAP signals of stromal cells became higher than that of tumor cells in the 8-week-old BxPC-3 tumors." (PMID 38891809, 2024). "68Ga-FAPI PET/CT targeting FAP-α has been used for the visualization of CAFs to detect tumor lesions in clinical settings; however, its value in assessing cancer response to immunotherapy is unknown." (PMID 38175716, 2024). "Beyond this, FAP regulates critical signaling pathways affecting both neoplastic and stromal cells, thereby enhancing angiogenesis, facilitating immune evasion, and promoting metabolic reprograming within the tumor milieu." (PMID 38826849, 2024). "Notably, B12 IgG can be internalized by FAP-expressing cells, as evidenced by its robust tumor accumulation." (PMID 38543239, 2024). "Consequently, our results underscore the need to validate FAP as a potential biomarker across various tumor types, clinical histories (treatment-naïve versus prior therapies), and treatment modalities." (PMID 38558814, 2024). "Analysis of tumor tissues at endpoint revealed that both U87 FAP+ and U251 FAP− cells were reduced following FAP‐CAR‐T cell treatment, suggesting that the CAR‐T cells exert longitudinal control over both U251 and U87 cells, in keeping with our in vitro findings of bystander killing." (PMID 38975278, 2024). "The ex vivo IHC analysis of the resected tumor tissue revealed distinctive FAP expression." (PMID 39335703, 2024). "However, directing therapies towards these FAP+ subtypes improves the tumor’s response to anti-PD-L1." (PMID 38835055, 2024). "Furthermore, clinical trials of FAP-2286 revealed prolonged tumor retention and superior tumor suppression compared with FAPI-46." (PMID 38543239, 2024). "Then, we demonstrated that FAP might contribute to tumor progression of HNSC through the PI3K-Akt signaling pathway, which provided the reference for understanding the role of FAP in tumor progression and its value in targeted therapy." (PMID 39055892, 2024). "In addition, the eNVs-FAP vaccine further enhanced the immune response against tumors by stimulating the release of γ-interferon from CTL and promoting the depletion of FAP-positive CAFs to promote tumor ferroptosis." (PMID 39174509, 2024).
tumor (continued). "In tumors, FAP expression is detected using near-infrared (NIR) fluorescent probes and quinoline-based FAP-targeted radiotracers (68Ga/18F-labeled FAP inhibitor [FAPIs]), which have shown intense tumor uptake and favorable image contrast capabilities in various tumors." (PMID 39758423, 2024). "Thus, FAP-targeted NIR-PIT induced TME immune remodeling resulting in activation of host tumor immunity and delay of tumor growth." (PMID 38555315, 2024). "The variability in the impact of FAP+CAF content across different cancers and TME pathways underscores the complexity of the tumor microenvironment and the need for a tailored approach in the use of FAP as a therapeutic target and as a biomarker to inform patient enrichment strategies." (PMID 39035007, 2024). "Furthermore, the specific anti-tumor immune responses also can facilitate cancer ferroptosis through the CTLs-derived interferon-gamma from and the depletion of FAP+CAFs." (PMID 38644492, 2024). "However, the upstream epigenetic mechanisms by which FAP drives tumor progression are unclear and warrant further investigation." (PMID 38459511, 2024). "We subsequently investigated the relationship between FAP expression and clinical outcomes in atezolizumab trials, both as monotherapy and in combination with anti-angiogenesis or chemotherapy, across four different tumor indications." (PMID 38558814, 2024). "Importantly, 177Lu-FAP-2286 exhibited commendable properties as an active targeting agent, characterized by potent and specific FAP binding, resulting in high tumor uptake, accumulation, and demonstrable therapeutic effects." (PMID 38543239, 2024). "Notably, this FAP+ POSTN+ CAF(c01_CST1) is significantly enriched in the tumor side, while myofibroblasts (c03_MYH11) show less proportion in this area." (PMID 39716897, 2024). "Targeting FAP-positive CAF in murine models has been shown to enhance anti-tumor immunity in several solid tumor models; a FAP-DNA vaccine induced CD8+ and CD4+ T-cells and synergised with other tumor antigen-specific DNA vaccines to enhance anti-tumor immunity." (PMID 38966131, 2024). "Indeed, the cyclic peptide-based [177Lu]Lu-FAP-2286 showed high and sustained tumor uptake and limited side effects in a first-in-man study (including one OC patient a.o.) ​95." (PMID 39431018, 2024). "Also, during another study in 2020, 92 CRC tissues and 19 normal tissues adjacent to the tumor tissue were examined in terms of FAP marker expression." (PMID 39030445, 2024). "Notably, PNT6555, when radiolabeled with actinium-225, demonstrated significant tumor growth inhibition, highlighting the potential of FAP-targeted alpha therapy." (PMID 39770505, 2024). "FAP is predominantly expressed in activated fibroblasts such as cancer-associated fibroblasts (CAFs) present in the tumor stroma, where they actively remodel the extracellular matrix (ECM) and influence tumor behavior." (PMID 39335703, 2024). "Hence, tumor growth and metastasis can be effectively inhibited using FAP antibodies, FAP-targeted radiopharmaceuticals, or silencing FAP expression." (PMID 39758423, 2024). "In this review we provide an overview of the current status of FAPI-PET, beginning with a brief description of FAP and FAP tracers, the importance of tumor stroma, and the potential clinical applications of this new class of PET tracers in comparison to FDG-PET." (PMID 40604259, 2024). "Thus, GC cells-derived BGN and CAFLCs-derived FAP played a critical role in regulating tumor growth and intraperitoneal dissemination of GC in co-injection." (PMID 36632455, 2023). "The binding of the peptides to murine FAP guarantees thorough evaluation of the diagnostic and therapeutic efficacies in non-humanized tumor-bearing mice models." (PMID 38706713, 2023). "Previous studies have shown that FAP has a great influence on tumor invasion and migration." (PMID 36382346, 2023).
tumor (continued). "FAP-immunohistochemistry of these same tissuesections showed moderate staining of FAP-expressing cells throughoutthe whole tumor, which appeared to be in stromal regions, and strongstaining of cells of unknown origin in the tumor borders." (PMID 37485886, 2023). "In conclusion, the present study provided the first multifactorial analysis of FAP in gastrointestinal cancers, revealing that the up-regulation of FAP in these cancers is correlated to tumor progression through promoting tumor cell motility as well as macrophages infiltration and M2 polarization." (PMID 37325617, 2023). "In contrast, FAP+ CAFs could promote tumor progression and depletion of FAP+ CAFs results in tumor suppression and improved survival." (PMID 37033924, 2023). "In addition, an increase in intra-epithelial CD8 levels occurred only in responding tumours, and FAP expression decrease in responders during the therapy." (PMID 36928373, 2023). "FAP has been confirmed to promote macrophage production in the tumor microenvironment and lead to an imbalance of M1/M2 macrophages, suggesting that FAP contributes to the recruitment and infiltration of other immune cells such as myeloid-derived suppressor cells (MDSCs) and neutrophils." (PMID 37006278, 2023). "There have been relatively few clinical studies conducted on FAP-targeted radionuclide therapy, and the results have been varied, which may be due to the multiple tumor types and patient conditions evaluated." (PMID 37376181, 2023). "Then we intended to investigate whether the up-regulation of FAP in tumor tissues correlated to DNA methylation of FAP promotor using UALCAN online tool." (PMID 37325617, 2023). "In vitro imaging confirmed a sustained high accumulation level of FAP-2286-ICG in tumor tissue." (PMID 38026901, 2023). "Furthermore, the tumor uptake of both tracers was reduced by ≥95% with the co-injection of FAPI-04 (250 μg), demonstrating that tumor uptake of both tracers is FAP-mediated." (PMID 36986548, 2023). "Moreover, tumor‐bearing mice who received immunization with rAd‐FAP/hlivin α‐transduced DCs showed higher survival rate compared with those receiving immunization with rAd‐hlivin α‐transduced DCs or rAd‐FAP‐transduced DCs alone." (PMID 37773704, 2023). "FAP is also involved in tumor growth, invasion, metastasis and immunosuppression." (PMID 37284857, 2023). "In these specific tumor types, FAP-specific TRT can directly kill the tumor cells." (PMID 38706713, 2023). "In this study, we examined the association between FAP and clinicopathologic parameters in our advanced NSCLC cohort and found that FAP was correlated with distant metastasis, which proved the tumor-promoting function of FAP in the invasion and metastasis of cancer." (PMID 35951090, 2023). "More importantly, FAP-positive CAFs are often abundant in the tumor microenvironment in more than 90% of epithelial carcinomas, while the FAP expression in normal tissues is usually undetectable, thereby making FAP a promising pan-tumor target for cancer diagnosis and therapy." (PMID 36864362, 2023). "Additionally, more studies are needed to determine if the function of FAP in FAP+ tumor macrophages is the same as we have described here in NK cells." (PMID 38196606, 2023). "In addition to its expression in the tumour microenvironment, increased FAP expression has also been detected in inflammatory diseases such as rheumatoid arthritis and fibrotic diseases." (PMID 37631053, 2023). "Despite their potential use in a wide spectrum of cancers, it is unclear whether CXCR4 or FAP expression clearly mark distinct tumor subgroups or certain tumor microenvironments." (PMID 36672341, 2023). "As FAP is a collagenase, its enzymatic activity is crucial in collagen degradation, which may assist in tumor growth." (PMID 38004406, 2023). "FAP plays a crucial role in the modulation of the tumor microenvironment." (PMID 38102692, 2023).